CD4 (CD4 molecule)
Diseases named in the same sentence as CD4 in open-access papers (continued):
Sharing a sentence is not in itself a finding about the gene and the disease.
infection (continued). "By contrast, CD4+ T cells exert their primary protective effect by secreting a range of cytokines, such as IFN-γ and TNF-α, which draw other immune cells to the infection site to promote differentiation of several CD4+ T cell subsets into effector cells that can eliminate Mtb." (PMID 37063832, 2023). "The total splenic CD4+ T cell count was comparable in both genotypes eight days after infection." (PMID 37812650, 2023). "While we could detect changes in the innate immune system reminiscent of infection, amyloid positivity was also accompanied by changes in adaptive immunity, particularly in CD4+ and CD8+ T cell phenotype and function." (PMID 37737298, 2023). "In addition to directly damaging endothelial cells, cytokines also promote lung-derived CCR9+ CD4 + T cells to enter the small intestine through the circulation mediated by CCL25 to achieve lung-intestinal axis infection." (PMID 37323898, 2023). "As expected from the short interval spanning between infection and sample collection, the maternal frequency of B cells, class-switched IgD– B cells, CD4+ T cells, activated CD4+ T cells, CCR6+ T cells, and CXCR5+ T cells remained equivalent in the presence or absence of symptoms." (PMID 37490342, 2023). "Interestingly, R-derived peptides from the Wuhan variant showed AIM+ CD4+ T cells during the pre-vaccination period, suggesting either asymptomatic SARS-CoV-2 infections or past infections with HCoVs." (PMID 37575243, 2023). "Congenic recipients (Thy1.1) were infected with MCMV-BAC or MCMV-B5 or uninfected, and CTV-labelled CD4-purified B5 TCR Tg T cells were adoptively transferred for the last five days of infection, testing presentation of B5 peptide between days 5–10, 25–30, or 55–60 of MCMV infection." (PMID 37205446, 2023). "Thus, removing membrane cholesterol using lipophilic cyclic oligosaccharide methyl-β-cyclodextrin (BCD) from B cells from PWOH prior to co-culture with CD4+ T cells inhibits HIV-1 trans-infection." (PMID 38140588, 2023). "If the amount of antigen presented to memory CD4 T cells at the resolution of infection is too high or too low, this quiescence state would be disrupted and could lead to defects in the memory development." (PMID 37908352, 2023). "The cell–cell contact during co-culture between Mø or DCs with CD4+ T-lymphocytes could favor the concentration of viral particles in a limited area of the donor cell membrane locally, increasing the multiplicity of infection." (PMID 37243118, 2023). "Moreover, HIG infusion would need to be highly effective, approaching 100%, to effectively prevent infection, particularly in CD4 T cell-depleted animals." (PMID 37896817, 2023). "Since the epithelial cell-derived cytokine IL-25 and IL-33 were known to mediate the progression of cryptococcal diseases caused by C. neoformans infection by amplifying Th2-type immune response, we further analyzed how IL-25 acted together with IL-33 to regulate CD4+ T helper cell during infection." (PMID 37337050, 2023). "Additionally, by comparing the numbers of Ifnγ+ cells from the different populations in the Med LN and lung at days 10 and 40 post-infection, we found that CD4 and CD8 T cells were the largest population of cytokine+ cells." (PMID 37842651, 2023). "Importantly, previous studies have shown similarities between immunodominant CD4 epitopes after infection and immunization." (PMID 37711622, 2023). "Infection of CD4+ T cells by SARS-CoV-2 alters cell function and triggers IL-10 production." (PMID 37523305, 2023). "Finally, we demonstrate the critical role of ATG9 in DC-SIGN-mediated autophagy flux activation and in contributing to dampening both HIV-1 capture in human dendritic cells and DC-mediated transfer of infection of CD4+ T lymphocytes." (PMID 37240354, 2023).
infection (continued). "Other studies have shown infection assays by inoculating spores of Coccidioides posadasii in HLA-DR4 transgenic mice (DRB1-0401 allele), which expresses human class II HLA, thus inducing the cellular response of T CD4+ lymphocytes." (PMID 37367569, 2023). "For example, ~ 90% of CD4 and CD8 T cell responses, from vaccinated individuals, against the S protein will still recognize the Omicron variant, while the cross-reactivity of CD8 T cell responses is lower after natural infection." (PMID 36752852, 2023). "The preference for IL2 production over IFNγ in SARS-CoV-2-specific T cells in this cohort may suggest a dominant role for cross-reactive central memory CD4 T cell responses in protection from detectable infection." (PMID 36901802, 2023). "We hypothesized that CD4+ T-cells may contribute to control of the infection through support of CCHFV-specific antibody responses." (PMID 37866114, 2023). "Like CD8+ T cells, the CD4+ T cell response emerges within the first year of infection." (PMID 38179040, 2023). "Looking further, we found an absolute increase, but proportional (% of CD4+) decrease in lung Tregs, suggesting that, whilst a regulatory response was emerging, it was dominated by Th2 inflammation during this relatively early stage of patent infection." (PMID 37012228, 2023). "This indicates that the expression of CTLA-4 on resting CD4+ T-cells may be a marker for a lower infection frequency of genetically-intact proviruses." (PMID 36776833, 2023). "Bacterial burden was significantly reduced in IL-10 KO mice in the brain and galea at day 14 post-infection compared to WT animals, concomitant with increased CD4+ and γδ T cell recruitment and cytokine/chemokine production, indicative of a heightened proinflammatory response." (PMID 37179295, 2023). "Also, CD4+ T cells’ ongoing responses against HCMV are associated with the control and clearance of infection." (PMID 37403036, 2023). "Gill is the only mucosal organ where down-regulation of gene encoding for CD4 and CD8 cytotoxic T cells markers were detected in koi on day 6 and 9 post-exposure to CEV genogroup IIa infection compared with control as well to the expression in CEV-infected AS carp." (PMID 37465154, 2023). "For example, HIV has been shown to downregulate CD4, the primary entry receptor, during infection." (PMID 38015055, 2023). "The deletion of Blimp-1 in T cells leads to a reduction of CD4+Foxp3+ T cells during the acute phase of infection and significantly decreased IL-10 production on day 12 post-infection, which could explain the observed increased inflammation." (PMID 37908369, 2023). "Here, CD4+ T cell-deficient mice with or without CD4+ T cells from wild-type mice were immunized with rEg.P29 and then subjected toE. multilocularis infection." (PMID 38151996, 2023). "The notable increase in the frequency of TN may help maintain the size and functionality of the patient’s CD4+ T-cell pool following breakthrough infection." (PMID 38140668, 2023). "Following infection, we saw an increase in the number of CD4+ T cells infiltrating the graft." (PMID 37676735, 2023). "We demonstrated that targeting inflammasome activation early after infection may represent a therapeutic strategy towards HIV cure to prevent CD4+ T cell depletion and reduce immune activation, viral load, and the HIV-1 reservoir formation." (PMID 36800238, 2023). "However, the number of splenic cytotoxic CD8+ T-cells and splenic helper CD4+ T-cells was comparable between the infected and uninfected birds across the course of infection." (PMID 38004824, 2023). "Moreover, EVs released from infected cells during infection with mycobacteria were shown to activate antigen-specific T cells in vivo (CD4+ and CD8+)." (PMID 37376186, 2023). "While CD4+ T cell responses against C. trachomatis are necessary for resolution of infection, CD8+ T cells and neutrophils may mediate the tissue damage seen in trachomatous scarring." (PMID 37862368, 2023).
infection (continued). "Vaccination with TBE vaccines induces protective antibodies, mainly against E, and CD4+ T cells against C and E. In contrast, natural infection with TBEV induces protective antibodies against E and NS1 as well as CD4+ (against C, E, and NS1) and CD8+ T cells (against NS2A, NS3, NS4B, and NS5)." (PMID 37153588, 2023). "It therefore may not be considered as a primary infection, nor a mechanism for latency of the virus, possibly allowing seepage of the virus into T-cells that are affected dually from and due to the primary infection of the CD4+ cells." (PMID 38155835, 2023). "However, early IL-17A production has also been described in mucosal CD3+CD4+ T cells after infection of naïve piglets with ETEC expressing F4 fimbriae." (PMID 37809062, 2023). "However, since CVB3 initiates infection in the intestine, we examined the CD4+ T cell response in the local lymph node following infection." (PMID 38274806, 2023). "Consequently, all agents that induce suppression of the CD4+ T lymphocyte-mediated immune response, such as FIV infection, can be considered risk factors for Leishmania infection." (PMID 38003815, 2023). "We next examined how different parasite-specific CD4+ T cell subsets differed in their sensitivity to STING activation following stimulation by culturing PBMCs from CHMI volunteers taken prior to infection and at day 15 p.i. for 72 hours with uRBCs or pRBCs with and without cGAMP." (PMID 37781920, 2023). "Indeed, previous studies in human experimental infection have shown that P. falciparum parasites rapidly induce Type I IFNs that drive development of regulator Tr1 CD4 T cells." (PMID 37968278, 2023). "For HTLV-1, the infection would strongly benefit from intercellular contact in this environment and could allow the virus to propagate in multiple CD4+ T cells in a timewise fashion." (PMID 36839454, 2023). "Induced deletion of the remaining Irf4 allele after infection further reduced frequencies of intestinal CD4+ T cells in the colon but not in the small intestine." (PMID 37469513, 2023). "However, memory CD4+ T cells in chronically Plasmodium‐infected mice show altered function in which they produced cytokines but proliferated poorly upon re‐infection with homologous parasites." (PMID 37855243, 2023). "A lower CD4 cell percentage often promoted higher infection rates of HR-HPV, HPV18 and HPV52." (PMID 37127618, 2023). "Evaluation of the maintenance of antigen-specific memory T cells unveiled that Lipo:LiChimera-immunized mice increased the numbers of effector memory CD4+ T cells as well as central memory CD8+ T cells during infection compared to the numbers estimated pre-challenge with the L. infantum parasite." (PMID 37631952, 2023). "Therefore, we sought to investigate the effects of IEC stimulation on the infection of activated CD4 + T cells." (PMID 37202790, 2023). "The massive depletion of CD4+ T cells in the gastrointestinal tract (GUT) during primary infection and the concomitant accumulation of inflammatory cells, such as dendritic cells, neutrophils, and monocytes, progressively compromise the mucosal integrity and disrupt the mucosal barrier." (PMID 36672667, 2023). "Moreover, the median CD4 count among those who were newly diagnosed long-term PLHIV were lower 352 cells/mm3 compared to those who newly diagnosed new infections 457 cells/ mm3." (PMID 36653851, 2023). "In summary, loss of a Tbx21 allele or timely induction of Eomes in activated CD4 T cells has no profound effect on the distribution during the early phase of an acute infection." (PMID 36756120, 2023). "The direct infection of resting or minimally activated CD4+ T cells to the latent reservoir may also play a role, particularly in very early, acute infection, but its importance later in infection is less clear." (PMID 37632019, 2023). "Thus, HIV bound on the dendritic cells can migrate through the epithelium promoting the infection of CD4+ cells." (PMID 36798134, 2023).
infection (continued). "The CD4/CD8 ratio remained unchanged even after breakthrough infection in both booster groups." (PMID 38140668, 2023). "The shift of the spike-specific CD4+ T cell population towards a regulatory phenotype may decrease the viral clearance of SARS-CoV-2 in these participants upon infection, further dampening their vaccine-induced protection." (PMID 38129594, 2023). "Similarly, SS18L2 mRNA was found to be upregulated in HIV-1 in early infection, as was found from the RNA profiling of CD4+ and CD8+ T cells in people living with HIV-1 versus those who were either nonprogressors or control HIV-1 negative groups." (PMID 37766271, 2023). "However, we found that IAV-specific lung CD4 T cells were more likely to express these molecules than those in spleen or Med LN prior to infection." (PMID 37842651, 2023). "It is obvious that further analysis of the experimental results of gene expression, duration of infection, CD4+ T cell count, and viral load may shed light on the molecular mechanisms of HIV infection progression." (PMID 36674980, 2023). "Programmed CD4+ T-lymphocyte death at the peak of infection might hinder specific immune responses and thereby SARS-CoV-2 eradication, favoring tissue lesions." (PMID 38235145, 2023). "However, a greater frequency of coinhibitory receptor–rich CD4+ T cell clusters were found in the liver, where infection was better controlled, compared with the spleen, where a chronic infection would be established." (PMID 37917177, 2023). "Our group and others have utilized ultrasound guided fine needle biopsy (FNB) or aspiration (FNA) to sample human LNs to quantify CD4+ T and B cell responses to infection and vaccination, including the work in progress by our group on LN responses to SARS-CoV-2 vaccines." (PMID 37508464, 2023). "Interestingly, the majority of CD4+ T cell significantly induced and enriched at 14 days post-infection was IL-17RB+ ST2+ cells." (PMID 37337050, 2023). "Notably, the production of IL-17 not only appeared to be involved in the generation of lung TRM cells but also played a critical role in TRM cell-mediated protection against infection, especially CD4+ TRM cells." (PMID 38093320, 2023). "Furthermore, this treatment influenced the migration of CD4 T cells in the early stages of infection, subsequently leading to a reduced T cell response and controlled proinflammatory signalling, thus mitigating inflammation." (PMID 38036985, 2023). "As such, CD4+ TN cells are resistant to infection by R5-tropic HIV-1." (PMID 38140588, 2023). "IL-6 was found to be involved in IEC induction of productive infection in resting CD4 + T cells." (PMID 37202790, 2023). "As before, we split all CD4+ T cells into a 70/30 (training/test) split by infection status." (PMID 36536105, 2023). "Additionally, the observation of the subtype-specific differences in CD4+ T cell level after primary infection is an indication that primary infection dynamics differ per subtype." (PMID 37161335, 2023). "The protective mechanism(s) of polyfunctional CD4+ T cells induced by vaccines or natural infection are still unknown." (PMID 37520577, 2023). "We show here that in Fiebig I prior to immune activation the only transcriptionally active and productive infections detectable are in resting CD4+ T cells, and, thus, this model cannot account for the origins of a latently infected cell population in the earliest detectable stage of HIV infection." (PMID 37733443, 2023). "However, using CD45.1 adoptive transfers, it is clear that few naïve CD8+ T cells are recruited to the site of infection, while CD4+ T cells are." (PMID 37696824, 2023). "Infection with C. perfringens also altered the frequency of CD4+ and CD8α + αβ T cells." (PMID 38164397, 2023). "Moreover, from an evolutionary perspective, infection of CD4+ T cells represents an effective mechanism for viruses to escape the immune response." (PMID 37523305, 2023).
infection (continued). "Finally, we compared the mRNA vaccine-induced populations of antigen-specific CD4+ T cells in the blood with antigen-specific CD4+ T cells obtained from a cohort of HLA-DPB1*04+ individuals following infection with SARS-CoV-2." (PMID 37790414, 2023). "Although the absolute numbers of PWH with low CD4+T-cell count < 200 cells/μL and mpox infection were very low (1.8% of all PWH with mpox), we found a more severe illness, with more generalized exanthema, more frequent pustular and hemorrhagic pattern, and with higher rates of hospitalization." (PMID 38004713, 2023). "Several studies suggest that memory CD4+ T cell fate is determined early during infection with Pcc." (PMID 37855243, 2023). "Thus, productive infection of resting T cells is expected to predominate whenever and wherever resting CD4+ T cells predominate in LT." (PMID 37733443, 2023). "We had shown a paradoxical persistence of HIV RNA+ cells despite initiation of ART in Fiebig I and now asked whether the persistent HIV RNA+ cells might be HIV-producing resting CD4+ T cells as a second source of virus for recrudescent infection." (PMID 37733443, 2023). "While DC-SIGN was reported to enhance trans-infection of CD4+ lymphocytes, this CLR was also reported to be essential for the regulation of MHC-I- and MHC-II-mediated antigen presentation upon HIV-1 internalization and for modulating TLR-driven innate immune responses." (PMID 37240354, 2023). "Overall, our results suggest that CD4 T cell help is efficiently recalled after infection; however, while it can accelerate GC formation and size, it might not be crucial to enhance the frequency of antigen-specific B cells within the GC." (PMID 37711622, 2023). "What’s more, preexisting memory CD4+ T cells, getting from infection by the common human coronaviruses, including HCoV-OC43, HCoV-229E, HCoV-NL63, and HCoV-HKU1, could realize cross-reactive with comparable affinity to SARS-CoV-2." (PMID 36726761, 2023). "Furthermore, the activation of CD4+ T cells was negatively correlated with CD4 counts before and after breakthrough infection, particularly in heterologous booster individuals." (PMID 38140668, 2023). "Finally, in a model of infection with Salmonella, resident macrophages expressing CXCL13 and CX3CR1 promote the infiltration of B and CD4+ T cells in areas of infection, where they are activated, giving rise to TLS induction." (PMID 37622111, 2023). "At termination after clearance of the infection (14 days after inoculation), samples of serum and vaginal wash were collected for antibody assay, and iliac lymph nodes were harvested for analysis of cytokine production by CD4+ T cells." (PMID 36537786, 2023). "Transient CD4+ T cell depletion prior to infection in mice results in viral chronicity." (PMID 36992265, 2023). "With regards to T cell responses, we observed that at 1 month post-infection 98.9% and 100.0% had a S-specific CD4 + and CD8 + T cell response, respectively, while at ten months post-infection, 89.7% and 93.8% had maintained a S-specific CD4 + and CD8 + T cell response, respectively." (PMID 37974069, 2023). "Overall, these findings suggest that an increasing number of Tex cells (PD-1+) are differentiated during the chronic stage of experimental infection with L. mexicana in response to tissue parasitism, highlighting that a greater number of CD4+ T cells exhibit an exhausted phenotype." (PMID 37691941, 2023). "We could previously show that during this stage of infection Tregs as well as CD8+ T cells negatively control the CD4+ CTL response against FV-infected cells as well as FV-transformed cells, while the molecular mechanism of this suppression remains unknown." (PMID 37965314, 2023). "Thus, our observations lead to the finding that SIV proviruses from later in infection (near start of therapy) are harbored in short-lived CD4+ T cells, while proviruses from earlier in infection are harbored in long-lived cells." (PMID 37961482, 2023).